CD4 (CD4 molecule)
Diseases named in the same sentence as CD4 in open-access papers (continued):
Sharing a sentence is not in itself a finding about the gene and the disease.
Allergy (continued). "Several researchers reported the essential contribution of CD4+ T cells in allergic diseases." (PMID 36713372, 2022). "Thus, in this type of allergic disease, skin-resident allergen-specific memory CD4 T cells are crucial for mediating local skin inflammation." (PMID 36591273, 2022). "The responses of CD4+CD25high Treg cells from paediatric subjects with or without allergy to H2O2 were similar to those observed in the same cell population from adult subjects with allergy." (PMID 34072455, 2021). "This immune reaction can be an allergic reaction with involvement of IgE and eosinophils or it could be a cell-mediated immune reaction conducted by CD4+ T lymphocytes." (PMID 34683832, 2021). "Effector/memory CD4+ T cells play an important role in allergic diseases." (PMID 34527063, 2021). "Overall, our data support previously reported immunomodulatory effects of pseurotins, which suggests a potential therapeutic usage of pseurotins in the treatment of diseases characterized by defective immune system such as allergic diseases, where especially CD4+ T cells play an important role." (PMID 33669259, 2021). "Furthermore, we verified that these effects of MQL on CD4+ T cells lead to alleviated allergic diseases such as an atopic dermatitis in vivo." (PMID 34356353, 2021). "Although Th2-type CD4+ T cells are not the sole source of these cytokines, numerous studies have established their requirement for the hallmark features of allergic diseases, including allergic asthma." (PMID 34305908, 2021). "Advantages of the present study include the performance of the DNA methylation analyses in purified CD4+ T cells, cells which are instrumental for development of specific long-term immune responses in general, but also for the development of allergic diseases in particular." (PMID 34193262, 2021). "In allergic diseases, two subpopulations of CD4+ cells play major roles: Th2 cells, which express transcription factor GATA binding protein 3 (GATA3) and induce the production of IgE, and regulatory T cells (Tregs) which are the main inducers of tolerance towards the antigens." (PMID 34394086, 2021). "Parity between our results using specific knockout of T cell–derived IL-10 and global blockade of pulmonary IL-10 signaling suggest that CD4+ Teff cells are the functionally dominant IL-10–producing cells for limiting IFN-γ responses in the lungs in patients with HDM allergy." (PMID 31445933, 2020). "Among related observations, nonatopic IgG may be related to thymic maturation of lymphocytes with an allergy inhibition-related cytokine profile induced by γδT cells as well as T CD4+ and CD8+ cells." (PMID 33027887, 2020). "Consistent with the results described previously in patients with allergy 15, the proportion and absolute number of CD4+IL-4+Th2 and CD4+IL-17+Th17 cells were significantly higher in splenocytes and lungs of asthmatic mice than in those from normal or PBS group." (PMID 32549755, 2020). "The superseding CD4+ T cell response is known as a hypersensitivity or allergy." (PMID 33374787, 2020). "In line with the protective effects that were observed on acute allergic symptoms and IgE, histone acetylation of Th2-related genes (GATA3, IL-4, IL-5, and IL-13) of splenocyte-derived CD4+ T cells after allergy induction was lower in raw milk-treated mice than in shop milk-treated mice." (PMID 31349704, 2019). "Furthermore, these results have implications beyond infectious disease, because CD4+ T cells are involved in antitumor immunity, and dysregulated CD4+ T cell function contributes to autoimmune and allergic diseases." (PMID 31391494, 2019). "Furthermore, allergy immunotherapy inhibited the increasing of IL-25 and Th2 cytokines IL-4, IL-5 and IL-13 with induction of CD4+CD25+ Foxp3+ Treg cells." (PMID 29784924, 2018).
Allergy (continued). "The regulation of IgG subclass switching of murine B cell by CD4+ CD25+ cells T helper cells has been very well studied in mouse models of allergy and it is evident that the ability of specific cytokines to generate specific differentiation is highly controlled in mice." (PMID 29164823, 2018). "Their team first demonstrated that only patients with a history of allergy could exhibit expanded Th2-type repertoires, and more importantly, clonal expansion of CD4+ cytotoxic lymphocytes (CTLs) were found to be involved in the pathogenesis of IgG4-RD31,32." (PMID 29968792, 2018). "Although these similarities suggest that B cells might be important for CD4 TRM generation, B cell deficiency led to enhanced Th2 TRM generation and maintenance in a house dust mite allergy model." (PMID 30386342, 2018). "Therefore, CD4+CD25+ TRegs play a crucial role in preventing inappropriate Th2 responses in allergic diseases." (PMID 31826046, 2018). "Th17 and Treg cells are the two main subsets of CD4+ T cells and participate in allergy responses." (PMID 30651897, 2018). "For example alterations to the immune responses in the gut directly affect the development of allergic disease in the lung, as dysbiotic mice display increased CD4+ T-cell mediated inflammation in the lung following allergen challenge compared to mice with a normal GI flora." (PMID 28604843, 2017). "CD4+ Th lymphocytes play a major role in the development of allergic disorders, and it is generally accepted that an imbalance in the different subsets of allergen-specific CD4+ T cells may result in the development of allergic diseases." (PMID 28740493, 2017). "In addition, we found that CD4(+) T cells are the immunological effectors of DNA vaccination in this allergy model." (PMID 27239481, 2016). "Our prior study showed that cytotoxic CD8+ Treg cells increasing expression of granzyme B may induce apoptosis of CD4+CD45RO+ memory T cells during allergy immunotherapy." (PMID 24475019, 2014). "The aim of the study was to investigate whether HIV-infected patients with CD4 cell counts <200 cells/μl can suffer from symptoms of IgE-mediated allergy, produce allergen-specific IgE antibody responses and show boosts of allergen-specific IgE production." (PMID 24896832, 2014). "In order to clarify the role of CD4+ and CD8+ T cells in the process of allergic disease caused by MP infection, we used intracellular cytokine staining combined with cell surface marker analysis to reveal if an increase in IL-4 production for MPP was associated with elevated IgE." (PMID 24977240, 2014). "Furthermore, we present strong evidence that indicate a central role for Treg (CD4+ CD25+ FoxP3+) in mediating allergy modulation in ocular allergy to hi-dose intraperitoneal sensitization." (PMID 24086630, 2013). "Allergy is a complex disease that is likely to involve dysregulated CD4+ T cell activation." (PMID 24116013, 2013). "During the initiation of allergy, the N- and/or C-terminal ends of proteolytic processing intermediates were preferentially loaded into antigen presenting proteins for the priming of CD4+ T cells." (PMID 18793409, 2008). "Measurement of Foxp3+CD4+ cells has the potential to aid in evaluating the presence of active inflammation, which cannot be evaluated by known Th1- and Th2-related markers in patients with allergic diseases." (PMID 23283296, 2008). "Because our results show that CD4+ T cells from a mouse model of allergy could still differentiate into Tregs under appropriate conditions of limited IL-4 and IFN-γ production, we consider that regulation of the cytokines may be useful for designing treatments using iTregs." (PMID 40446078, 2025). "The goal of this study was to determine whether CFTR negatively regulates CD4+ T cell differentiation and effector function in allergic disease and if strategies to increase CFTR function may provide therapeutic potential in airway inflammation through T cell direct and indirect mechanisms." (PMID 40131363, 2025).
Allergy (continued). "The CFTR modulator drug class may provide pharmacological approaches to managing common and persistent type 2 inflammation in CF via epithelial and CD4+ T cell mechanisms, while more broadly representing a new class of therapies to be repurposed for allergic disease." (PMID 40131363, 2025). "Similarly, in autoimmune and allergic diseases that are CD4+ T cell–dependent, T-helper polarization, or in MHC class II–restricted diseases, SDHA inhibition could mitigate autoimmune/allergic disorders." (PMID 41392980, 2025). "However, profiles of infiltrating Tomato+ CD4+ T cells were distinct in OVA feeding, tolerance, and allergy conditions, suggesting that iSellTomato is an effective system for enriching and characterizing polyclonal intestinal CD4+ T cells responding to food protein in different contexts." (PMID 37191720, 2023). "Therefore, in the present study, high dose of leptin should negatively impact the prognostic of allergic diseases due to the ability of this adipokine in reducing functional Treg/Tr-1 and TFR cells, CD4 T cell subset implicated in controlling Th2/Th9 and TFH2/TFH13 axis respectively." (PMID 37954580, 2023). "Thus, in this review, we summarize the recent findings on allergen-specific memory CD4 T cells and their external homeostatic microenvironments that mediate the pathology of allergic diseases such as allergic asthma, atopic dermatitis (AD), and food allergies (FA)." (PMID 36591273, 2022). "Although allergen-specific CD4+ Th2 cells instigate the allergic responses, notably through the production of IgE directed towards mite allergens, recent studies have demonstrated that innate immune activation also plays an important role in mite-induced allergy pathogenesis." (PMID 34566947, 2021). "In the context of IgE-mediated allergy, activated MCs have been reported to induce an increase in infiltrating neutrophils, which respond to local cytokines by presenting antigen to specific CD4+ effector T-cells that release IL-5 to activate eosinophils and increase the synthesis of IgE." (PMID 32958528, 2020). "Thus, one could envision that iBALT skews CD4 T cell differentiation away from a Th2 pathway and thereby attenuates the symptoms of allergic disease." (PMID 33101290, 2020). "Furthermore, an examination of the proportion of Th2 lymphocytes induced in the small intestinal lamina propria revealed that p.o. administration of C. koseri yielded an increased proportion of CD4+ IL-4+ lymphocytes (Th2 lymphocytes) in OVA-specific allergy mice." (PMID 31611274, 2019). "In support of a protective role of n-3PUFA, it has been shown that DHA-induced suppression of allergic reactions was accompanied by increased forkhead box P3 (FoxP3)+CD4+ regulatory T cells, and intradermal injection of regulatory T cells could inhibit skin inflammation." (PMID 31518521, 2019). "The balance between pro-inflammatory CD4+ Th2 cells and regulatory T cells, including CD4+Foxp3+ regulatory T cells (Treg) and CD4+Foxp3-, interleukin-10 (IL-10)-producing Type one regulatory T cells (Tr1) cells, is a significant determinant in the development of allergic disease." (PMID 31603425, 2019). "Th17 cells are a new type of CD4+ T cells and mainly exert inflammatory action by secreting orphan nuclear receptor yt (RORyt) and other effector cytokines such as IL-17A and IL-6, which can induce allergic asthma, systemic lupus erythematosus, rheumatoid arthritis, and other allergic diseases." (PMID 30651897, 2018). "However, an elevated risk for hepatic alteration and allergic reaction was not demonstrated in pregnant women exposed to nevirapine with CD4 > = 250 cells/mm3 in our cohort." (PMID 30261855, 2018). "However, avoiding activation of the TLR-mediated immune pathway appears safer than a desensitization approach for preventing allergic disease development in the offspring of allergic pregnant women since the latter can up-regulate CD4+CD25+ T cells and IL-10 production in offspring." (PMID 27646403, 2016).
Allergy (continued). "Additionally, we recognize that our coexpression network may have yielded distinct results had we chosen a different tissue for gene expression profiling; we had chosen to study peripheral blood CD4+ lymphocytes given their central role in allergic disease." (PMID 25085501, 2014). "Because we found that pathogenic T cells infiltrated into inflammatory lesions of nude mice that had received transferred T cells derived from mice with metal allergic disease, we further investigated whether CD4+ or CD8+ T cells were preferentially involved in Pd allergy." (PMID 24533050, 2014). "In T cells, several tetraspanin proteins, including CD9, CD81 and CD82 are reported to associate with CD4 or CD8 and enhance T cell effector functions, while CD81 negatively modulates FcεRI-mediated degranulation in mast cells and suppress IgE-dependent allergic reactions." (PMID 24832104, 2014). "However further studies might be necessary to clarify the mechanism how vitamin D is able to control the activity of CD4+ T cells and the related Th2-type cytokines in the pathogenesis of allergic disease." (PMID 25061262, 2014). "In addition, our data suggest that hi-dose sensitization may henceforth facilitate the further examination of CD4+ CD25+ FoxP3+ Treg in allergic disease." (PMID 24086630, 2013). "In our birth cohort study, decreased CD4+CD25+ T-cell levels were significantly correlated to PM10, benzene and moderately to NO2 indicating that by decreasing Treg cells, pollutant exposure might increase the risk of allergy in newborns." (PMID 22047167, 2011). "Namely, the vast majority of allergy epitopes were defined for B cells/antibodies (and in these records, IgE-mediated reactivity figured prominently), and relatively fewer T-cell epitopes (mostly defined as CD4+/class II, with very few being defined for CD8+/class I)." (PMID 21403821, 2010). "CD4+ TRM cells can influence lung epithelial cells to enhance neutrophilic inflammation during pneumonia, but if they do so in settings of allergy is uncertain." (PMID 39965565, 2025). "More importantly, the NK cells with TSC22D3 deficiency promoted CD8+ T cell responses and a shift from promoting proliferation of CD4+ T to CD8+ T cells, implying an important role for the innate immune system in regulating drug-induced allergic disease." (PMID 40544157, 2025). "Memory CD3+CD4+ T cells are derived from a cell population that experienced a specific antigen but remained in the body after said antigen was no longer present, where they may be protective against cancer but also be involved in auto-immunity, allergy, and chronic inflammation." (PMID 39763680, 2024). "Our network analysis identified distinct clusters, including lymphocyte-birth, CD4+ - CD8+, lung function, and allergy-FeNO, highlighting complex relationships between lymphocyte profiles and clinical characteristics." (PMID 38336805, 2024). "Important for the context of allergic diseases is the fact, that CD38+ CD4+ T cells were characterized to be hypo-proliferative with a specific bias towards IL-13 secretion (with no change toward IL-4 or IL-5 secretion)." (PMID 38318168, 2024). "Despite the Th2 bias of both CME and PN allergies, IL-4-mediated regulation of CD152 on the surface of CD4+ T cells after challenge with PN was seen in PN and NA donors but not in CME donors." (PMID 38067164, 2023). "In both tissues, CD4+ T cell influx was increased over twofold in OVA allergy mice, while OVA tolerance fell between feeding and allergy." (PMID 37191720, 2023). "scRNAseq data of intestinal CD4+ T cells from GF or Oligo-MM12 mice fed AA, AA + OVA, or chow diet, and SPF iSellTomato mice in the OVA feeding, tolerance, or allergy protocols are publicly available under Gene Expression Omnibus accession number GSE231351." (PMID 37191720, 2023). "Although CD4+ T cells play a major role in the development of such a vaccine, Seneviratne and colleagues showed that CD8+ T cells also play a role in allergic reactions." (PMID 37987298, 2023).
Allergy (continued). "During the effector phase of allergic response, NK cell depletion increased the number of OVA-specific CD4+ T cells and the levels of IL-23, IL-17A, and IFN-γ." (PMID 37448795, 2023). "We further explored the relationship between the level of CD4+CCR6+CRTh2+ memory Th2 cells and history of allergic diseases such as AR and AD." (PMID 34090369, 2021). "Conversion of CD4+CD25+FOXP3+ T regulatory cells (Tregs) from the immature (CD45RA+) to mature (CD45RO+) phenotype has been shown during development and allergic reactions." (PMID 34072455, 2021). "CD4+CD25+ T cells have been reported to contribute to the alleviation and prevention of allergic diseases." (PMID 32184789, 2020). "We assessed histone acetylation at the promoter regions of Th1-, Th2-, Th17-, and Treg-related genes of splenocyte-derived CD4+ T cells and MLN to determine the role of epigenetic mechanisms in the allergy-protective effect of raw milk." (PMID 31349704, 2019). "A major finding was that 35.2% and 38.5% of cord blood samples have low PKCζ (≤the 5th percentile of adult levels) in the CD4+ and CD8+ subsets, respectively, consistent with the incidence of allergy development in the population." (PMID 31239481, 2019). "It was demonstrated that CD4+CD25+Foxp3+ natural Treg cells and inducible type 1 Treg cells inhibit the development of allergy via several pathways." (PMID 29921316, 2018). "There were fewer CD4+CD25+FOXP3+ T cells present in both the neonates with allergic mothers and the neonates who developed allergies in early childhood." (PMID 27646403, 2016). "Due to its role in priming of naïve CD4+ T cells towards a Th2 response, TSLP has been described to have an essential role in the initiation of allergic diseases." (PMID 27769179, 2016). "On the other hand, CD4+CD25+ cells occasionally mediate peripheral tolerance, leading to an exacerbated inflammatory/allergic reaction or autoimmunity." (PMID 26564056, 2015). "Oral administration of L. plantarum NRIC0380 lyophilized powder was reported to suppress IgE production in β-lactoglobulin-immunized BALB/c mice and the induction of regulatory T cell (CD4+CD25+Foxp3+; Treg) was involved in the anti-allergy activity." (PMID 24936861, 2014). "Moreover, human allergen‐DNA‐transfected DCs were verified to stimulate CD4 and CD8 T cells and had the potential for treatment of IgE‐mediated allergic diseases." (PMID 40765419, 2025). "Moreover, P4 had a notable effect on the immune microenvironment within the lungs, fostering a balance between Th1/Th2 and Treg/Th17 cells, CD4+ T cells, and controlling NETosis initiated by OVA-induced allergies." (PMID 39060348, 2024). "One study evaluated naïve CD4 T cell‐specific methylation using the EPIC micro‐array in blood samples of adolescents with and without an IgE‐mediated food allergy, finding higher methylation in the allergy group for a DMR of seven probes." (PMID 38808605, 2024). "By contrast, in the large intestine, there was no increase in CD4+ T cell influx in tolerance or allergy mice, suggesting that responses to food in inflammatory contexts remain localized to the small intestine." (PMID 37191720, 2023). "To assess whether CD4+ T cells that mature and enter the gut during OVA feeding, tolerance, or allergy have distinct characteristics, we compared cluster distributions of Tomato+ cells between these groups." (PMID 37191720, 2023). "Polyclonal CD4+ T cell responses to food, including TCR-specific selection and functional differentiation, remain largely uncharacterized and are critical for understanding mechanisms of tolerance and allergy." (PMID 37191720, 2023). "In the present study, similar downregulation of CD4 T cell responses was observed in mouse allergy among ENA laboratory animal-care workers ARE to mouse allergen, as evidenced by a decrease both in proportion of activated 4-1BB+OX40+ CD4 T cells and in IFN-γ and IL-5 cytokine production." (PMID 33616085, 2021).